SFRP2 (secreted frizzled related protein 2)
Diseases named in the same sentence as SFRP2 in open-access papers (continued):
Sharing a sentence is not in itself a finding about the gene and the disease.
intestinal cancer (1 paper, 2024). "In the human intestinal cancer specimen, the broad colocalization but local anticorrelation of IGHG4 and SFRP2 may reflect the involvement of humoral immunity in combating the cancer." (PMID 38168288, 2024). "Again, in human intestinal cancer, the tradeoff between IGHG4 and SFRP2 transcripts specifically where both are abundant is not detected by pairwise correlation nor by ME delineation." (PMID 38168288, 2024).
invasive breast carcinoma (1 paper, 2024). A carcinoma that infiltrates the breast parenchyma. "For the five genes (LPL, PCK1, KRT6B, SFRP2, SHC2) that were differentially expressed between the datasets, we analyzed the alterations in metastatic breast cancer and invasive breast cancer genetic profiles." (PMID 38791477, 2024).
lobular carcinomas (1 paper, 2007). "Of the differentially expressed genes involved in Wnt signaling, SFRP2 (secreted frizzled-related protein 2) and WISP1 (WNT1 inducible signaling pathway protein 1) were upregulated in lobular carcinomas." (PMID 17389037, 2007).
lupus (1 paper, 2024). "In lesional CLE biopsies, these same inflammatory profiles were reflected in single-cell RNA-Seq of SFRP2+ and inflammatory fibroblast subsets, and TGF-β was identified as a critical upstream regulator for inflammatory fibroblasts in scarring discoid lupus lesions." (PMID 38358820, 2024).
muscle disorders (1 paper, 2018). "This suggests that baseline levels of sFRP2 are present in healthy skeletal muscle and play a protective role against various muscle disorders." (PMID 30151071, 2018).
nasal polyp (1 paper, 2024). "Interestingly, within the CRS subtypes, there was very high expression of SFRP1 and SFRP2 in CRSsNP, which suggests that fibroblasts may regulate EpC Wnt signaling in CRS and highlights the possibility that unopposed EpC Wnt signaling may contribute to nasal polyp formation." (PMID 38444858, 2024).
nasopharyngeal carcinoma (1 paper, 2018). A carcinoma arising from the nasopharyngeal epithelium. "Furthermore, we found that Wnt5B, SFRP1, and SFRP2 were hypermethylated in nasopharyngeal carcinoma tissues, and the hypermethylation of DKKs and DACTs in nasopharyngeal carcinoma tissues was also confirmed." (PMID 30075814, 2018).
oral lichen planus (1 paper, 2025). Oral lichen planus is a chronic inflammatory oral condition of unknown aetiology characterized by T-cell-mediated chronic immune response and abnormal epithelial keratinization cycle. "Taken together, these results reveal that SFRP2+ fibroblasts contribute to inflammatory cell infiltration and are in close proximity to CD8+ T cells in the superficial layer of the lymphocyte infiltration zone in oral lichen planus." (PMID 40574847, 2025).
oropharyngeal cancers (1 paper, 2015). Carcinoma, predominantly squamous cell, arising from the epithelial cells of the oropharynx. "In this regard, frequent hypermethylation of the negative regulators of this pathway (DKK-3, RUNX3, SFRP1, SFRP2, SFRP4, SFRP5, and WIF1) was observed in oral and oropharyngeal cancers." (PMID 25487617, 2015).
peritoneal disease (1 paper, 2022). "In addition to the presence of peritoneal disease, by the transcriptome analysis of paired samples of neoplastic tissue and normal gastric mucosa, we have identified a group of six differentially expressed genes that predict poor prognosis: ONG, FABP1, LIF, ONECUT2, SFRP2, and GPA33." (PMID 35847866, 2022).
prediabetes (1 paper, 2021). "Further studies are needed to explore whether sFRP2 is associated with prediabetes and whether this association, if any, is involved in CVDs and HF." (PMID 34722660, 2021).
pterygium (1 paper, 2022). A wedge-shaped fibrovascular lesion arising from the bulbar conjunctiva and extending to the cornea. "We finally chose night genes to verify their expression levels, including the other two genes (SFRP2 and SFRP4) involved in Wnt signaling; Their expression levels were significantly different between pterygium and conjunctiva." (PMID 36187094, 2022).
pulpitis (1 paper, 2020). Inflammation of the dental pulp. "Firstly, we investigate the SFRP2 expression in pulpitis, and the real‐time RT‐PCR and immunohistochemistry results showed that the expression of SFRP2 was decreased in pulpitis tissues compared with that in normal pulp tissues." (PMID 31568642, 2020). "In present study, we discovered that the expression of SFRP2 was decreased in pulpitis tissues." (PMID 31568642, 2020).
rectum tumor (1 paper, 2019). "Consequently, we focused our study on SFRP2 methylation in rectum tumor samples." (PMID 31319558, 2019).
retinal degeneration (1 paper, 2021). Degeneration of the retina. "BMP and sFRP2 antagonism also enhanced CE cell proliferation in response to exogenous growth factor stimulation and MNU-induced retinal degeneration." (PMID 34717744, 2021).
retinitis pigmentosa (1 paper, 2013). Retinitis pigmentosa (RP) is an inherited retinal dystrophy leading to progressive loss of the photoreceptors and retinal pigment epithelium and resulting in blindness usually after several decades. "Interestingly, in another degenerative eye disease, retinitis pigmentosa (RP), immunostaining for SFRP2 and β-catenin showed up-regulation of SFRP2, but no clear β-catenin differences." (PMID 23825088, 2013).
sarcoma (1 paper, 2016). A usually aggressive malignant neoplasm of the soft tissue or bone. "Presently there are pre-clinical monoclonal antibodies targeting sFRP2, which could provide biological evidence for the role of this molecule on sarcoma progression." (PMID 27821163, 2016).
schizophrenia (1 paper, 2024). A major psychotic disorder characterized by abnormalities in the perception or expression of reality. "Within this gene set, the difference between AT-schizophrenia subjects and control pairs correlated either positively (WNK1) or negatively (SFRP2) with age." (PMID 38648100, 2024).
squamous cell carcinoma (1 paper, 2023). A carcinoma arising from squamous epithelial cells. "A significantly lower SFRP2 protein concentration was found in the total NSCLC tumour samples and the following NSCLC subtypes: squamous cell carcinoma (SCC) and adenocarcinoma (AC) (p > 0.05, p = 0.028 and p = 0.001, respectively)." (PMID 37999144, 2023). "This is the first study to evaluate the concentrations of SFRP1, SFRP2, and SFRP5 in tumour and non-tumour (NT) samples from patients with primary NSCLC, including adenocarcinoma, squamous cell carcinoma, and large cell carcinoma." (PMID 37999144, 2023).
syndactyly (1 paper, 2019). A disease characterized by the presence of syndactyly, including syndromic and non-syndromic forms. "Mice lacking Dkk1 (dickkopf Wnt signaling pathway inhibitor 1) or Sfrp2 (secreted frizzled-related protein 2), genes encoding soluble inhibitors of Wnt signaling, develop syndactyly." (PMID 30679680, 2019).
tendinopathy (1 paper, 2025). "Our findings demonstrated that FHL2 supplementation after tendon injury can noticeably decrease YAP1/sFRP2 expression, inhibit vascular remodeling associated with tendinopathy and restore tissue structure despite some differences from normal tendon tissue." (PMID 41258071, 2025). "By contrast, downregulation of FHL2 expression and upregulation of YAP1/sFRP2 expression are strongly and positively correlated with the temporal pathological remodeling and angiogenesis associated with tendinopathy." (PMID 41258071, 2025). "This study revealed that low FHL2 expression-induced upregulation of YAP1/sFRP2 may be a critical mechanism underlying vascular remodeling in tendinopathy." (PMID 41258071, 2025). "sFRP2 expression in tendinopathy is associated with the Hippo/YAP1 signaling pathway." (PMID 41258071, 2025). "This study employed exercise-induced (treadmill) and trauma-induced rat tendinopathy models to investigate the FHL2/YAP1/sFRP2 axis in the context of angiogenesis." (PMID 41258071, 2025). "This study reveals that FHL2/YAP1/sFRP2-mediated vascular remodeling drives tendinopathy progression." (PMID 41258071, 2025). "In conclusion, this study systematically explored the progression of tendinopathy and its pathological relationship with vascular instability, highlighting the critical role of vascular remodeling via the FHL2/YAP1/sFRP2 signaling axis." (PMID 41258071, 2025). "Thus, in tendinopathy, FHL2 overexpression may primarily suppress inflammatory angiogenesis via its anti-inflammatory effects, thereby improving perfusion and promoting repair, potentially mediated by the YAP1/sFRP2 axis." (PMID 41258071, 2025).
thymoma (1 paper, 2022). A neoplasm arising from the epithelial cells of the thymus. "SFRP2 and SFRP5 expression levels were increased in B2 thymomas, while AB thymomas showed increased DKK1 and DKK4 expression compared to other TETs and NTs." (PMID 35965500, 2022).
urothelial carcinoma (1 paper, 2022). A malignant neoplasm derived from the transitional epithelium of the urinary tract (urinary bladder, ureter, urethra, or renal pelvis). "Correlations between tumoral SFRP2 expression and other important clinicopathological parameters in urothelial carcinomas." (PMID 35372028, 2022). "Correlations between stromal SFRP2 expression and other important clinicopathological parameters in urothelial carcinomas." (PMID 35372028, 2022).
vitiligo (1 paper, 2020). Generalized well circumscribed patches of leukoderma that are generally distributed over symmetric body locations and is due to autoimmune destruction of melanocytes. "Profilaggrin (gene name FLG), a protein hormone that promotes hair growth, and SFRP2, a soluble regulator of WNT signaling, were significantly upregulated in VKH but not vitiligo." (PMID 33384688, 2020).
tumor (156 papers, 2007 to 2025). "The SFRP2 gene methylation in serum samples was found to be associated with a poor grade of differentiation, high tumor-node-metastasis stage coupled with +ve lymph node metastasis and deep cancer invasion in the wall tissue." (PMID 40109625, 2025). "SFRP2 is frequently hypermethylated in many tumors, and its downregulation is closely associated with Wnt signaling activity and tumor progression." (PMID 39729237, 2025). "Stromal SFRP2 expression was higher in recurrent samples (p = 0.009) and protein expression in primary tumours was associated with worse patient survival (p = 0.022)." (PMID 38361045, 2024). "We found that the location of the tumor (colon vs. rectum) was associated with promoter SFRP2 methylation (p < 0.05)." (PMID 38802858, 2024). "We used this pipeline to identify KIF5B and SFRP2 as very promising early protein biomarkers secreted by tumor remodulation events associated with cancer cells interacting with naïve stromal cells." (PMID 36002889, 2022). "The secreted frizzled-related protein 1 and 2 genes (SFRP1 and SFRP2) encode antagonists of the Wnt signaling pathway, acting as tumor suppressors." (PMID 33030559, 2021). "Our results also showed that SFRP2 methylation was associated with TIAM1 promoter methylation in CRC tumor area from the > 30th CRC patients." (PMID 32517740, 2020). "The role of sFRP2 protein was associated with Wnt signaling pathway and several studies reported the key role of this protein in tumor progression and aggressiveness." (PMID 29304852, 2018). "We show that only SFRP1 associates consistently with tumour suppressive functions, and that SFRP2 and SFRP4 typically associate with a poor prognosis concomitant with the expression of genes associated with epithelial-to-mesenchymal transition." (PMID 28218291, 2017). "SFRP2 has been identified as a modulator of the Wnt signaling pathway, which is associated with multiple tumor types, including GC." (PMID 25202403, 2014). "Additionally, studies have found that low expression of sFRP2 in BCa tumor tissues is associated with poor prognosis." (PMID 40016549, 2025). "Furthermore, SFRP2 overexpression was also associated with increased tumor size and reduced survival rates in BCa." (PMID 37965470, 2023). "Furthermore, recently enhanced sFRP2 expression has been associated with promoting therapeutic resistance and metastatic potential within solid tumors by specifically altering the tumor microenvironment." (PMID 27821163, 2016). "In conclusion, SFRP2 may represent a candidate class II tumor suppressor gene whose altered expression is caused by epigenetic changes (class II) rather than by mutation (class I)." (PMID 18990230, 2008). "Alternatively, this failure could be explained by the likely involvement of SFRP2 methylation in the early steps of breast carcinogenesis, rather than being implicated in the development of prognostically adverse tumor subtypes." (PMID 18990230, 2008). "Therefore, the aim of this study is to test whether there is a significant association between SFRP2 DNA methylation and other cancer outcomes, such as survival rates, response to therapy, location, or recurrence in blood and tumor samples." (PMID 38802858, 2024). "However, SFRP2 expression was associated with tumor formation, and the downregulated expression of this gene may increase the risk of malignancies." (PMID 33589441, 2021). "Furthermore, several studies consider abnormal methylation of SFRP2 as a noninvasive diagnostic and prognostic biomarker of CRC, suggesting that SFRP2 might be implicated in cancer development, but also as a tumor suppressor gene." (PMID 32517740, 2020). "Thus, this association could display TIAM1 and SFRP2 as two candidates to be potential tumor suppressor genes." (PMID 32517740, 2020). "Combined with multiplex immunofluorescence, it revealed metabolically inactive tumor regions enriched in SFRP2+ CAFs and Tregs, forming immunosuppressive niches resistant to chemotherapy." (PMID 41020873, 2025).
tumor (continued). "After comprehensive and robust multidimensional validation, incorporating differential expression analyses and survival assessments, three key tumor stemness-associated genes—REN, AQP1, and SFRP2—were carefully compared." (PMID 40534868, 2025). "In this study, we selected RNF180 and SFRP2 genes from GC patients, patients with precancerous gastric lesions, and healthy individuals, and compared and co-analyzed them with conventional tumor markers (CEA, CA199, and CA125)." (PMID 39541711, 2024). "Targeting SFRP2 with antibodies shows antiangiogenic effects in tumor models, presenting a promising therapeutic avenue for inhibiting tumorigenesis and metastasis." (PMID 38474093, 2024). "In our study, we found that SFRP2 methylation in whole blood is a potential biomarker for several cancer outcomes, while SFRP2 methylation in tumor tissue is a promising predictor for therapy response, suggesting its potential use in clinical practice." (PMID 38802858, 2024). "We also observed that the performance of RNF180 and SFRP2 combined with traditional tumor markers to predict GC (AUC=0.858) was slightly better than that of the combination of the RNF180 and SFRP2 alone (AUC=0.844)." (PMID 39541711, 2024). "When comparing the effects of RNF180 and SFRP2 with traditional tumor markers (CEA, CA125, and CA199), significant differences were found between the GC and healthy individual groups for all five genes." (PMID 39541711, 2024). "| Conversely, overexpression of SFRP2 in cancer cell lines and tumor tissues has also been reported." (PMID 39850884, 2024). "In our study, we determined the global β methylation of the SFRP2 gene in the tumor and NAT area using DNA array." (PMID 38802858, 2024). "As a result, we discovered that global β methylation of the SFRP2 gene was higher in the tumor area than in the NAT area (p < 0.001) in both TCGA-COAD and -READ." (PMID 38802858, 2024). "We found that SFRP2 methylation in the tumor area was significantly higher than that in the NAT area, but not for SFRP2 expression, probably due to the sample size." (PMID 38802858, 2024). "To improve the sensitivity of detecting GC, we included 78 GC patients and 124 healthy individuals in the training set and divided them into three groups: RNF180 and SFRP2 (RS), a tumor marker group (CEA, CA125, and CA199), and a group with RS + tumor marker." (PMID 39541711, 2024). "Conversely, the over expression of SFRP2 in cancer cell lines and tumor tissues has also been described." (PMID 39850884, 2024). "Out of 273 tumours analysed, 26 (9.5%) exhibited mutations or amplifications in AHRR, while 7 (3%) displayed copy number changes (amplifications and deletions) in SFRP2." (PMID 38361045, 2024). "Global β methylation of the SFRP2 gene was higher in the tumor area, when compared to the NAT area (p < 0.001)." (PMID 38802858, 2024). "SFRP2 acts as a tumor suppressor, and many studies have shown that SFRP2 downregulation occurs due to promoter hypermethylation in several types of cancer." (PMID 39850884, 2024). "Our results show that AHRR (tumour suppressor) and SFRP2 (oncogene) are differentially expressed between primary and recurrent tumours both on the gene and the protein level and furthermore act as protein-based prognostic markers for HGSOC." (PMID 38361045, 2024). "On the other hands, multiple studies have reported that SFRP2 is hypermethylated in tumor tissue from CRC patients." (PMID 38802858, 2024). "Since SFRP2 is primarily expressed in stromal cells and silenced in tumors, as scRNASeq analysis showed, this phenomenon can elucidate its role as a tumor suppressor gene." (PMID 38802858, 2024). "Using blood as a non-invasive clinical tool, these studies found that SFRP2 methylation was predominantly hypermethylated in blood samples, including circulating tumor cells (CTCs), in serum, circulating free DNA, and plasma." (PMID 38802858, 2024).